MMP2 (matrix metallopeptidase 2)
Diseases named in the same sentence as MMP2 in open-access papers (continued):
Sharing a sentence is not in itself a finding about the gene and the disease.
cholesteatoma (continued). "Sixty patients with cholesteatoma under 15 years old, who underwent their primary surgery at Aichi Medical University's Otolaryngology Department, were analyzed for MMP2 expression level, using RNA-in situ hybridization." (PMID 33778077, 2021). "Herein, we analyzed MMP2 mRNA expression level in cholesteatoma using RNA-in situ hybridization in formalin-fixed, paraffin-embedded (FFPE) tissue samples." (PMID 33778077, 2021). "In acquired cholesteatoma, higher MMP2 mRNA signals were observed in the pars tensa type than in the pars flaccida type (p < 0.001)." (PMID 33778077, 2021). "We used RNA-ISH to identify MMP2 mRNA expression level in the tissue specimens from patients with cholesteatoma." (PMID 33778077, 2021). "In acquired cholesteatoma, higher MMP2 signals were observed in the pars tensa than in the pars flaccida (p < 0.001)." (PMID 33778077, 2021). "Considering the high expression of MMP2 mRNA in the aggressive types of cholesteatoma, it is plausible that MMP2 plays a critical role in the progression of aggressive cholesteatoma." (PMID 33778077, 2021). "Two of the enzymes proven to play an important role in the pathogenesis of cholesteatoma are Matrix metalloproteinase-2 (MMP-2) and Matrix metalloproteinase-9 (MMP-9)." (PMID 34682191, 2021). "Among them, matrix metalloproteinase-2 (MMP2) was reported to play an important role in cholesteatoma progression, by promoting bone destruction and keratinocyte invasion." (PMID 33778077, 2021). "In congenital cholesteatoma, higher MMP2 mRNA signals were observed in the open type than in the closed type (p < 0.001)." (PMID 33778077, 2021). "In congenital cholesteatoma, higher MMP2 signals were observed in the open type than in the closed type (p < 0.001)." (PMID 33778077, 2021). "Specific cholesteatoma MMP isoenzymes (MMP2, MMP3, and MMP9) were first identified in 199617 with the use of immunohistochemistry tests." (PMID 22714856, 2012). "While that paper was being published, the concept of MMP2 tissue invasion was used in relation to cholesteatomas in this study." (PMID 17505599, 2007). "Cholesteatoamas express MMP2 and Invasive cholesteatomas had high MMP2 compared to latent cholesteatomas." (PMID 17505599, 2007). "Banerjee, James and Narula15 (1997) by means of the Western blotting technique, showed the presence of metalloproteinase 2 (MMP2) in cholesteatomas." (PMID 17505599, 2007). "Our goal with the present investigation is to observe if cholesteatomas in general produce matrix metalloproteinase 2 (MMP2), and if more aggressive cholesteatomas produce a higher quantity of MMP2." (PMID 17505599, 2007). "The reading of the MMP2 immunohistochemical expression in the cholesteatoma slides was expressed in values of: 0 (Attenuated), + (Mild), ++ (Moderate) and +++ (Intense)." (PMID 17505599, 2007). "Of the cholesteatomas that presented complications, eight of the nineteen: one had attenuated MMP2 expression (12.5%), three expressed MMP2 moderately (37.5%), and four strongly expressed MMP2 (50%)." (PMID 17505599, 2007). "With respect to latent cholesteatomas, higher expression of MMP2 was observed in 27.3% (3 cases), with Fisher's exact test indicating a significant difference (p=0.015)." (PMID 17505599, 2007). "A similar role for MMP-2 is observed in cholesteatoma tissue." (PMID 38535082, 2024). "Furthermore, IL-1α induces osteoclast function and increases bone matrix degradation, and it is known that MMP-2 and MMP-9 also cause bone matrix degradation for patients with cholesteatoma." (PMID 38535082, 2024). "Still, we believe that our data indicates that MMP-2 expression is correlated with the biology of cholesteatoma, and it is possible that MMP2 expression might be used as a prognostic marker or surrogate marker for recurrence of cholesteatoma." (PMID 33778077, 2021).
cholesteatoma (continued). "MMP2 mRNA expression level is suggested to contribute to the aggressiveness of cholesteatoma, and thus, MMP2 inhibition may be a therapeutic option for cases featuring MMP2 upregulation." (PMID 33778077, 2021). "The findings suggest that the level of expression of MMP2 mRNA may be related to the pathogenesis and aggressive features of cholesteatoma." (PMID 33778077, 2021). "MMP2 mRNA expression might be used as a prognostic or surrogate marker for recurrence of cholesteatoma." (PMID 33778077, 2021). "Upregulation of MMP2 mRNA level in aggressive cholesteatoma raises the possibility that MMP2 may be a promising therapeutic target." (PMID 33778077, 2021). "Yet, it is still unclear how exactly TIMP-2 affects MMP-2 or MMP-9 in cholesteatoma tissue." (PMID 34682191, 2021). "Another assumption we may suggest is that when we operate on a patient with cholesteatoma, if we carry out an MMP2 immunohistochemical reaction, we may increase the prognostic accuracy on the operated lesion." (PMID 17505599, 2007). "We analyzed the expression of MMP2 in invasive (causing complications) compared to latent cholesteatomas (not causing complications)." (PMID 17505599, 2007). "Higher expression of MMP2 was observed in 7 (87.5%) of the 8 invasive cholesteatomas." (PMID 17505599, 2007). "In Chart 1, we may also notice that of eight patients with invasive cholesteatomas, only one had a lesser MMP2 expression; the remaining patients with invasive cholesteatomas manifested a higher MMP2 expression (++ and +++)." (PMID 17505599, 2007). "However, serum levels of MMP2 might be affected by systemic inflammatory conditions, which prompted us to quantify the amount of MMP2 in the cholesteatoma tissue." (PMID 33778077, 2021). "MMP‐2 and MMP‐9 not only modulate inflammatory responses through pro‐inflammatory cytokine release in cholesteatoma microenvironments, but also have been characterized in histopathological specimens as a biomarker predictive of ossicular chain destruction." (PMID 40837198, 2025). "TREM2 amplifies the inflammatory response of the TLR4 signaling pathway, promoting the secretion of MMP-2 and MMP-8 and the excessive activation of osteoclasts, thereby facilitating bone destruction induced by acquired cholesteatoma." (PMID 40242752, 2025). "Marimastat is a broad‐spectrum matrix inhibitor targeting matrix metalloproteinases (MMPs), including MMP‐2 and MMP‐9, demonstrating therapeutic potential for cholesteatoma‐related pathologies." (PMID 40837198, 2025). "We substantiate this by the increased amount of MMP-2 and decreased TIMP-2 in the cholesteatoma groups compared with control skin, as well as positive correlations between MMPs and TIMPs in the cholesteatoma tissue." (PMID 38535082, 2024). "Our results revealed that higher MMP2 mRNA signals were observed in stage II or III cholesteatoma, compared to stage I cholesteatoma." (PMID 33778077, 2021). "In human acquired cholesteatoma, the expression of proinflammatory cytokines (IL-1β, TNF-α and IL-6) and matrix metalloproteinases (MMP-2, MMP-8 and MMP-9) were up-regulated, and their expression levels were positively correlated with TREM-2 expression." (PMID 27934908, 2016). "MMP-2 and MMP-9 are not only found in OM with effusion but also in pediatric patients with cholesteatoma, a chronic stage of otitis media." (PMID 22655080, 2012). "Back in 1998, Banerjee, James and Narula demonstrated that MMP2 and MMP9 were present in cholesteatomas and in the external auditory canal skin." (PMID 17505599, 2007). "The intercorrelations we found among IL-1α and MMP-2 and MMP-9 may support the theory that MMP activity is also regulated by IL-1α in cholesteatoma tissue." (PMID 38535082, 2024). "MMP2 is a core member of the MMP family, consisting of proteolytic enzymes that degrade the extracellular matrix, and is known to play an important role in cholesteatoma progression via bone destruction and tumor cell invasion." (PMID 33778077, 2021).
cholesteatoma (continued). "The numbers of MMP-2-positive cells in the cholesteatoma matrix ranged from a lack of positive cells to moderate or numerous positive cells (++/+++)." (PMID 34682191, 2021). "In Chart 1, of the 11 patients with latent cholesteatomas, 2 had no MMP2 expression, six patients had MMP2 expression of +, and 3 patients expressed MMP2 as ++." (PMID 17505599, 2007). "Of the cholesteatomas that did not present clinical complications, eleven of the nineteen studied, two of them expressed attenuated MMP2 (18.1%), six expressed MMP2 with mild intensity (54.6%), three expressed MMP2 with moderate intensity (27.3%)." (PMID 17505599, 2007). "However, previous studies have focused on quantifying serum MMP2, and MMP2 expression level in cholesteatoma lesions has not been well investigated." (PMID 33778077, 2021). "Therefore, the MMP expression levels were tested using Real-time PCR, and the results revealed that the expression levels of MMP-2 (p < 0.01), MMP-8 (p < 0.001) and MMP-9 (p < 0.01) were significantly increased in human acquired cholesteatoma (n = 10) compared with the normal skin (n = 10)." (PMID 27934908, 2016).
clear cell renal cell carcinoma (13 papers, 2015 to 2026). "MMP-2 and -9 are reported in literature to be associated with poor prognosis in kidney clear cell carcinoma." (PMID 31200666, 2019). "NNMT induces cellular invasion via activating PI3K/Akt/SP1/MMP-2 pathway in clear cell renal cell carcinoma (ccRCC)." (PMID 36817086, 2023). "A subsequent study has indicated that NNMT promotes clear cell renal cell carcinoma invasion and metastasis by inducing matrix metalloproteinase 2 (MMP2) expression." (PMID 35756670, 2022). "For instance, in clear cell renal cell carcinoma (ccRCC), elevated ROS production activates the MAPK signaling pathway, leading to the overexpression of matrix metalloproteinase-2 (MMP2), a protease responsible for degrading ECM components." (PMID 40563367, 2025). "After treatment of clear cell renal cell carcinoma cells with LGK974, the expression levels of β-catenin, cyclin D1, c-Myc, MMP9, and MMP2 were significantly decreased." (PMID 33923996, 2021). "Previous studies have confirmed that HMGN5 regulates the expression of MMP2 and MMP9 via c-jun and then contributed to the migration and invasion of clear cell renal cell carcinoma (ccRCC) cells." (PMID 31930127, 2019). "Higher expression of MMP-2 and MMP-9 are found in patients who have kidney clear cell carcinoma metastases when compared to patients without distant metastases." (PMID 31200666, 2019).
tongue cancer (13 papers, 2010 to 2025). A malignant neoplasm affecting the tongue. "Those hub genes involved in pathways of cancer are Bcl2, EGFR, ESR1, MMP9, PPARG, and MMP2 and those involved in PI3K-Akt signaling pathways are Bcl2, EGFR, CDK2, and MCL1 these genes are considered therapeutic targets for tongue cancer." (PMID 39863836, 2025). "In the orthotopic transplanted tongue carcinoma in mice model, we confirmed that HF administration inhibited tumor growth and lymph node metastasis (LNM) with reduced CAF population, MMP2 expression and collagen deposition in tumor." (PMID 36506509, 2022). "It was also demonstrated that emodin inhibited protein levels and activities of matrix metalloproteinase-2 (MMP-2), the gene expression of MMP-9, and the migration and invasion of human tongue cancer SCC-4 cells." (PMID 34073059, 2021). "In other words, expression of MMP-9 protein was significantly increased in tongue cancer cells with strong proliferative ability, although such correlation was not significant for MMP-2." (PMID 23107277, 2012). "In tongue cancer cells, ERK1/2 and MMP2 pathways appeared to be crucial, but not E7-pRB and AKT pathways." (PMID 31830929, 2019).
arthropathy (12 papers, 2009 to 2024). Any disorder of the joints. "The first variant inherited from her father is the missense substitution in the MMP-2 (matrix metalloproteinase-2) gene that is associated with “Multicentric osteolysis, nodulosis, and arthropathy” (OMIM # 259600), caused by homozygous variants." (PMID 39595064, 2024). "The MMP2 gene is linked to the “Multicentric osteolysis, nodulosis, and arthropathy” disease in OMIM (OMIM:259600), a disease that covers the phenotypes observed in the patient." (PMID 37479972, 2023). "Deficiency of matrix metalloproteinase 2 (MMP-2) causes a complex syndrome characterized by multicentric osteolysis, nodulosis, and arthropathy (MONA) as well as cardiac valve defects, dwarfism and hirsutism." (PMID 33101055, 2020). "Multicentric osteolysis, nodulosis and arthropathy (MONA) spectrum disorder is a rare inherited progressive skeletal disorder caused by mutations in the matrix metalloproteinase 2 (MMP2) gene." (PMID 27687687, 2016). "Multicentric osteolysis, nodulosis, and arthropathy are caused by at least eight mutations in the matrix metalloproteinase-2 (MMP2) gene, which is a rare inherited bone disease characterized by loss of bone tissue (osteolysis), especially in the hands and feet." (PMID 35093162, 2022). "Genetic Analysis identified a homozygous pathogenic variant in exon 2 of the matrix metalloproteinase 2 (MMP2) gene [c.301C>Tp(Arg101Cys)] confirming the diagnosis of Multi-centric Osteolysis Nodulosis and Arthropathy (MONA)." (PMID 39463871, 2024). "Multicentric Osteolysis, Nodulosis, and Arthropathy (MONA MIM #259,600) is the best term to describe the phenotypes together due to MMP2 variants as a cause of disease in our patients." (PMID 37710205, 2023). "Specifically, homozygous inactivating mutations of the matrix metalloproteinase 2 (MMP2), MMP14, or SH3PXD2B genes may cause defective collagen remodeling and result in the allelic variants of MONA (multicentric osteolysis, nodulosis and arthropathy), Torg or Winchester syndrome." (PMID 38681749, 2024). "Elevated MMP-2 and MMP-9 activities have been detected in synovial fluid from various joint diseases in man, but in the equine, few data on synovial gelatinase activities are recorded." (PMID 32111016, 2020). "It is worth adding that the high concentrations of MMP-2 and -9 in the synovial fluid and in the serum of children with JIA prove the presence of the increased degradation of type II collagen already in the early stages of arthropathy." (PMID 33924892, 2021). "The lack of effect on MMP-2 is not surprising and is consistent with the literature indicating the greater significance of MMP-9 in joint diseases than MMP-2." (PMID 19664212, 2009).
cutaneous melanoma (12 papers, 2015 to 2023). A primary melanoma arising from atypical melanocytes in the skin. "In general, the expression of MMP2, MMP13, MMP16, MMP17 and MMP25 were significantly associated with skin cutaneous melanoma (SKCM) patients prognosis, among which MMP2 low expression benefited patients the most." (PMID 36788565, 2023). "MMP-2 was examined in several other cancers, such as lung adenocarcioma, pancreas cancer, and primary skin melanoma." (PMID 32751899, 2020). "A non-cytotoxic concentration of OC (10 μM) was demonstrated to inhibit migration and invasion of human skin malignant melanoma A375 and A2058 cells, possibly via downregulation of matrix metalloproteinase-2/9 (MMP-2/9)." (PMID 29734791, 2018). "Multiple studies have shown that MMP2 is among the strongest prognostic markers for cutaneous melanoma." (PMID 25784655, 2015). "In addition, it has been validated that MMP2 and MMP9 are implicated in the development and metastasis of cutaneous melanoma." (PMID 29108247, 2017). "Multiple studies have revealed an increased expression of MMP-2 in TME including cancer of the colorectum, ovaries, breast, prostate, bladder, lung, and pancreas, in addition to primary skin melanoma and central nervous system (CNS) malignancies." (PMID 32751899, 2020). "The overexpression of MT1-MMP and MMP-2 is regulated by phosphoinositide 3-kinase (PI3K), and specific inhibitors of PI3K are able to abrogate vasculogenic mimicry in both uveal and cutaneous melanoma cells by decreasing the levels of MT1-MMP and MMP-2." (PMID 31212986, 2019). "In the presented study, we have evaluated a clinical utility of the concentrations of VEGF, MMP-2, MMP-9, TIMP-1, and YKL-40 in serum of patients with skin melanoma at locoregional disease." (PMID 26002577, 2015). "The aim of the study was to define clinical utility of serum biomarkers: VEGF, MMP-2, MMP-9, TIMP-1, and YKL-40 in patients with skin melanoma at locoregional stage." (PMID 26002577, 2015).
dilated cardiomyopathy (12 papers, 2015 to 2025). Cardiomyopathy which is characterized by dilation and contractile dysfunction of the left and right ventricles. "Given that elevated plasma levels of MMP-2 have been observed in patients with congestive HF, regardless of the underlying cause (such as acute MI, dilated cardiomyopathy, or valvular disease), MMP-2 may serve as a potential biomarker." (PMID 40305314, 2025). "Increased levels of matrix proteases such as MMP2 and MMP9 were observed in heart tissue obtained from a patient with dilated cardiomyopathy." (PMID 30116150, 2018). "Increased MMP2 and MMP9 levels are known in patients with dilated cardiomyopathy." (PMID 37512106, 2023).
hyperlipidemia (12 papers, 2014 to 2025). "Our research reveals that hyperlipidemia induces an upregulation of MMP2/9 levels in the vascular wall, leading to the loss of vascular elastic fibers and subsequent dysfunction in vascular relaxant function." (PMID 38992615, 2024). "In the present study, tissue protein levels only demonstrated an association among active MMP-2 and the prevalence of hyperlipidemia and higher levels of active MMP-2 in the group of patients with hyperlipidemia." (PMID 30794673, 2019). "As only hyperlipidemia revealed an association with active MMP-2, we conducted regression analyses only for the hyperlipidemic subgroup." (PMID 30794673, 2019). "The estrogen signaling pathway was regulated by CA binding to HSP90AA1, MMP2, RARA, PRKACA, ESR1, MMP9, and ESR2 in this present research, which underlies the improvements observed in hyperlipidemia and thrombosis." (PMID 38398534, 2024). "Our work has also shown that although hyperlipidemia abolished the beneficial effect of ischemic preconditioning, cardioprotection in the presence of hyperlipidemia was preserved during pharmacological inhibition of MMP-2." (PMID 29674965, 2018). "In our study, immunoblotting and IHC for MMP2 and MMP9 was used to investigate hyperlipidemia-induced fibrosis in renal tissue." (PMID 35845925, 2022). "Furthermore, hyperlipidemia has also been shown to increase ROS production through activation of NOX, induction of matrix metalloproteinase 2 (MMP2), and stimulation of macrophage infiltration." (PMID 33546200, 2021). "Circulating levels of MMP-2 and MMP-9 have been found to increase in patients with acute and chronic lower limb ischemia (i.e., intermittent claudication and critical ischemia), as well as in patients with hyperlipidemia when compared with healthy subjects." (PMID 31963569, 2020). "Active MMP-2 was significantly higher in the group of patients with ascending aortic aneurysm and hyperlipidemia compared to those without hyperlipidemia (p = 0.009)." (PMID 30794673, 2019).